KLF11 (KLF transcription factor 11)
Diseases named in the same sentence as KLF11 in open-access papers (continued):
Sharing a sentence is not in itself a finding about the gene and the disease.
tumor (19 papers, 2012 to 2024). "KLF11 also has a dual function in cell growth and cancer as a tumor suppressor and a tumor promoter." (PMID 38396943, 2024). "In summary, there was a high degree of consistency in cellular functional assays suggesting that KLF11 promotes tumor cell growth via promoting cell proliferation and/or suppressing cell apoptosis of BC." (PMID 37199905, 2023). "Multivariate cox regression analysis was further applied with the univariate significant factors: grading, tumor size, lymph node status and KLF11 expression." (PMID 37199905, 2023). "Multivariate cox analysis was then applied with the univariate significant factors: molecular subtype, grading, tumor size, lymph node status and KLF11." (PMID 37199905, 2023). "The result revealed that KLF11 (HR = 2.610, 95% CI = 1.241–5.488, p = 0.011), grading (HR = 2.260, 95% CI = 1.262—4.047, p = 0.006) and tumor size (HR = 2.624, 95% CI = 1.384 − 4.975, p = 0.003) were independent factors for poor DFS." (PMID 37199905, 2023). "The result showed that KLF11 (HR = 2.744, 95% CI = 1.017–7.403, p = 0.046), grading (HR = 3.276, 95% CI = 1.424 – 7.536, p = 0.005), and tumor size (HR = 5.729, 95% CI = 2.266 − 14.484, p < 0.001) were independent factors for poor DMFS." (PMID 37199905, 2023). "KLF11 showed an up-regulation in BPA+ condition, with an increasing trend along with neutron irradiation, consistent with previous findings in which radiotherapy induces overexpression of KLF11, suppressing tumor progression through apoptosis activation." (PMID 37371031, 2023). "The results showed that tumor formation in nude mice injected with KLF11-OE cells was significantly suppressed compared to the KLF11-NC group (Fig. 7fa-b–g)." (PMID 37248295, 2023). "Biologically, this HP1-HMT recruitment is required for KLF11-mediated gene regulation and tumor suppression." (PMID 22318730, 2012). "We verified the effects of promoter DNA methylation on transcriptional inhibition of three tumor suppressor genes namely, KLF11, DLEC1, and KRT19." (PMID 22428009, 2012). "We selected three genes, the known tumor suppressors KLF11, DLEC1, and KRT19 and verified promoter hypermethylation, mRNA repression and protein expression using bisulfite sequencing, real-time PCR and western blot." (PMID 22428009, 2012). "Furthermore, different groups of nude mice were treated with FINs or chemotherapeutic agents during tumor proliferation, and it was found that the tumors in the KLF11-OE group regressed significantly compared to KLF11-NC+GPX4 and KLF11-OE+GPX4 groups." (PMID 37248295, 2023). "Moreover, the public databases showed aberrant expression of KLF11 in multiple tumor tissues and KLF11 has been shown to play a crucial role during tumorigenesis and development." (PMID 37248295, 2023). "Clinicopathologically, we also found that KLF11 was low expressed in the LUAD tumor tissues compared to adjacent normal tissues, and the level of KLF11 was negatively correlated with the expression of GPX4 but positively correlated with the prognosis of LUAD patients." (PMID 37248295, 2023). "The underlying mechanism that reported for KLF11 in other types of cancer, whereby the role of KLF11 is reversed when the environment changes from a normal to a tumor situation, might also happens in BC." (PMID 37199905, 2023). "In this way, KLF11 behaves as a tumor suppressor gene by repression of the cPLA2α–PGE2 pathway." (PMID 32331236, 2020).
tumor (continued). "On the contrary, direct tumor-promoting effects of KLF11 have also been described." (PMID 32331236, 2020). "Deletion of the C-terminus leads to deregulation of tumor suppression functions mediated by KLF11." (PMID 24885560, 2014). "Biologically, impairment of KLF11-mediated HP1-HMT recruitment abolishes tumor suppression, providing direct evidence that HP1-HMTs act in a sequence-specific manner to achieve this function rather than its well characterized binding to methylated chromatin without intermediary." (PMID 22318730, 2012). "Due to the importance of HP1 recruitment in KLF11-mediated gene expression and the fact that KLF11 is a well established tumor suppressor, we subsequently investigated the significance of this mechanism for several cellular processes associated to this function." (PMID 22318730, 2012). "Therefore, it is worth exploring whether KLF11 actually acts as an oncogene or a tumor suppressor in BC, and then implying its potential ability to be a therapeutic target for BC patients." (PMID 37199905, 2023). "This indicates that KLF11 might act as a tumor-suppressor in BC." (PMID 37199905, 2023). "Therefore, a full understanding of the role of KLF11 in growth control and tumor progression will not only requires an analysis of the individual factor KLF11 but also the identification of all KLFs expressed in the cells of interest and the characterization of the transcriptional context." (PMID 32331236, 2020). "Therefore, KLF11 might participate in the functional switch of TGF-β from a tumor suppressor to a tumor promoter." (PMID 32331236, 2020). "Subsequently, we initiated investigations into whether the interaction between HP1 and KLF11 was necessary for KLF11-mediated tumor suppression, by measuring the rate of apoptosis and cell proliferation, two well known cellular mechanisms underlying this phenomenon." (PMID 22318730, 2012). "The high expression of CREB in LUAD patients’ tumor tissues and KLF11 in RSL3/IKE-treated A549 and PC9 cells further supports the idea that CREB or KLF11 are positive or negative regulators of antioxidant defense." (PMID 37834062, 2023). "For example, KLF family proteins have been shown to have either a tumor-promoting (KLF4, KLF6, KLF9, KLF10, KLF11, and KLF17) or a tumor-suppressing (KLF5, KLF12) role by intervening in cell signaling associated with proliferation and/or suppression." (PMID 26320172, 2015). "From this set, we then selected three of the hypermethylated genes, Kruppel-like transcription factor 11 (KLF11), deleted in lung and esophageal cancer 1 (DLEC1), keratin 19 (KRT19) for further analysis based on their known tumor suppressor functions." (PMID 22428009, 2012). "Furthermore, we identified some potential prognostic biomarkers for HCC, a highly malignant tumor with high incidence and mortality rates, including AFP, H2AC19, KLF11, and IFNG." (PMID 37107646, 2023). "Due to the established role of both KLF11 and HP1 in gene regulation, we reasoned that these proteins may exert a tumor suppressor function, at least in part, by modulating gene expression." (PMID 22318730, 2012).
cancer (17 papers, 2010 to 2025). A tumor composed of atypical neoplastic, often pleomorphic cells that invade other tissues. "KLF11 was epigenetically silenced in OS cancer stem cells (CSCs), causing sustained YAP/TEAD activation." (PMID 36499521, 2022). "Mechanistically, this data demonstrates that HP1 binding to KLF11 triggers a distinct transcriptional response, which includes many genes involved in cancer-associated events." (PMID 22318730, 2012). "Klf11, which has been reported for its role as an inducer of oligodendroglial cell death downstream of Tgfß signaling and Elk3, which is essential for neural crest development and associated with cancer progression were also highlighted." (PMID 41446274, 2025). "The role of KLF11 in several cancer types is mainly growth-related, such as cell proliferation or cell apoptosis." (PMID 37199905, 2023). "Although some studies have identified the roles of KLF11 in cancer biology, the functions of KLK11 in other metabolism-related diseases are still covered." (PMID 34059001, 2021). "In KRAS oncogenic mutant cancer cells, KLF11 inhibits BrdU incorporation, increases apoptosis, and inhibits the KRAS-mediated foci and agar colony formation." (PMID 32331236, 2020). "Of additional interest, for some of the genes confirmed here, such as DAZAP2 and KLF11, very little is known about their involvement in cancer and metastasis." (PMID 23113900, 2012). "Nevertheless, with the well established role of many of these co-regulated targets in cancer (34%), their silencing by HP1 via interaction with KLF11 is congruent with the role of this protein in cancer-related processes." (PMID 22318730, 2012). "Compared with empty vector, co-transfection with KLF11 decreased cPLA2α promoter activity in three different cancer cell lines, namely in FLO cells (66 ± 3.3%), SEG-1 (54.4 ± 5.8%), and SKGT-4 (by 45 ± 9%) (p < 0.05)." (PMID 20154088, 2010). "Additionally, when the premalignant lesions develop into malignant tumor, the role of KLF11 has shown to be reversed due to the active of previously silenced oncogenic pathway." (PMID 37199905, 2023). "KLF8 and KLF11 have also been shown to be involved in OS cancer stem cell induction." (PMID 36499521, 2022). "In the last decade, the transcription factor KLF11 has come into focus in cancer research." (PMID 32331236, 2020). "KLF11 is expressed in a number of human tissues, and it is repressed in several human cancers." (PMID 22428009, 2012). "However, DAZAP2 is essential for neural patterning in Xenopus laevis embryos, and KLF11 is an activator of embryonic and fetal beta-like globin genes, again pointing to a connection between regulation of embryonic development and cancer invasion." (PMID 23113900, 2012). "However, the role of KLF11 in normal cell growth regulation and cancer is diverse, and other KLFs might induce relevant transcription responses as well." (PMID 32331236, 2020). "KLF11 has previously been shown to play a crucial negative role in cancer stem cells in non-OS tumors." (PMID 36499521, 2022).
metabolic disease (5 papers, 2012 to 2024). A congenital disorder (due to inherited enzyme abnormality) or acquired (due to failure of a metabolically important organ) disorder resulting from an abnormal metabolic process. "Kruppel-like factor 11 (KLF11 or TIEG2) is a zinc finger transcription factor that has been implicated in the regulation of complex metabolic diseases." (PMID 26861594, 2016). "The coordinated regulation of KLF10 and KLF11 manifests in bone cell development, bone diseases, and certain metabolic disorders." (PMID 39272379, 2024). "The effect of KLF11 on EC metabolic dysfunction during diabetic atherosclerosis and other metabolic disorders creates potential new avenues for further investigation." (PMID 39462409, 2024).
infection (3 papers, 2010 to 2014). The state of being infected such as from the introduction of a foreign agent such as serum, vaccine, antigenic substance or organism. "As expected, Ad-KLF11 infection reduced glucose production in primary mouse hepatocytes in the presence of FSK and Dex." (PMID 24586865, 2014). "Subsequently, we measured levels of insulin secreted from INS-1 cells after infection with adenovirus carrying empty vector, KLF11 WT, or KLF11 A347S by ELISA." (PMID 23589285, 2013). "Next, we overexpressed KLF11 using AdvKLF11 infection of cells to assess if KLF11 can regulate cell proliferation." (PMID 20154088, 2010). "Under these conditions, infection with KLF11 decreased the BrdUrd-positive cells by up to 50% in vehicle-treated cells." (PMID 20154088, 2010).
neurodegenerative disease (2 papers, 2020 to 2025). A disorder of the central nervous system characterized by gradual and progressive loss of neural tissue and neurologic function. "KEGG pathway analysis implicated neurodegenerative diseases pathways and highlighted target genes associated with long-term depression signaling and tryptophan metabolism, including RIN2, TCF7L1, DDIT4, and KLF11." (PMID 41009397, 2025). "Moreover, the TF genes FSOL2, KLF11, and NEF2L2 play essential roles in the neurodegenerative diseases." (PMID 32149119, 2020).
endocrine disorders (1 paper, 2014). "Wild type KLF11 possessed the most unique networks (n = 10) and included a number of characterized biological and disease networks, including cellular growth and proliferation, endocrine disorders, reproductive system development and function, and biliary hyperplasia, among others." (PMID 24885560, 2014).
renal disease (1 paper, 2022). "Although several KLF proteins have been implicated in the pathogenesis of renal disease, a potential role for KLF11 has not previously been established." (PMID 35413089, 2022).
retinopathy (1 paper, 2024). "The frequency of retinopathy was low, and the presence of microalbuminuria was 0% in ABCC8‐MODY and KCNJ11‐MODY, while microalbuminuria ranged from 1.8% in HNF4A‐MODY and HNF1A‐MODY to 16.7% (1 out of 6 individuals) in KLF11‐MODY." (PMID 39511990, 2024).
KLF11 also shares sentences with these, for which no sentence is quoted: abdominal aortic aneurysm (2 papers); Insulin resistance (2); ovarian carcinoma (2); Alzheimer disease (1); anemia (1); asthma (1); Atrophy (1); brain infarction (1); Cerebral ischemia (1); congenital disorder of glycosylation (1); coronary artery disease (1); dyserythropoietic anemia (1); endothelial dysfunction (1); genetic diseases (1); Hypertension (1); maturity-onset diabetes of the young (1); mental disorder (1); mood disorder (1); myeloid malignancies (1); neonatal diabetes mellitus (1); reproductive system diseases (1); uterine diseases (1); Uterine leiomyoma (1); Vestibular schwannoma (1); viral infection (1); Zinc deficiency (1).